SPARC (secreted protein acidic and cysteine rich)
Diseases named in the same sentence as SPARC in open-access papers (continued):
Sharing a sentence is not in itself a finding about the gene and the disease.
tumor (continued). "Macrophage-derived cathepsins, SPARC, or CCL18 improve tumor cell adhesion to extracellular matrix proteins and promote tumor cell migration." (PMID 36613819, 2022). "However, whether NCAPG promotes NSCLC tumor metastasis through SPARC should be further studied." (PMID 35180865, 2022). "We also observed that high SPARC and WNT3A expressions in the tumor stroma had a significant influence on OS (HR 0.55 for higher versus low expression, CI 0.30-1.00, P=0.050; HR 0.54 for higher versus lower expression, CI 0.30–0.99, P=0.046; respectively)." (PMID 36452484, 2022). "The correlation of SPARC and TPM1 expression and clinicopathological parameters, including tumor stage, tumor grade and lymphnode metastases, was analyzed by UALCAN database." (PMID 35477379, 2022). "In cancer models, SPARC has been shown to affect ECM components, cell adhesion, tumor growth, migration, apoptosis, and chemosensitivity." (PMID 35965624, 2022). "We also observed a significant influence for better OS by higher SPARC and WNT3A expression in tumor stroma." (PMID 36452484, 2022). "Preclinical evidence suggests that SPARC deletion has stimulating effects on ischemic retinopathy, RNV and tumor angiogenesis by enhancing VEGF and MMP9 expression." (PMID 34795670, 2021). "In the context of TAMs, essential factors that control tumor angiogenesis include members of the SEMA family, S100A family, chitinase-like proteins, osteopontin, SPARC, COX-2, Tie2, and others." (PMID 34209679, 2021). "SPARC displayed anti-tumorigenic properties by regulating ECM deposition and inhibiting the growth of tumor cells." (PMID 33466303, 2021). "When the same analyses were done using PEA Oncology II profiling data, 10 proteins correlated to tumor stage (P < 0.05), for example, CD160, TNFRSF4/OX40L, XPNPEP2, SPARC, MAD homolog 5/SMAD5, CPE, hK8/KLK8, WIF‐1, TCL1A, and MIC‐A/B." (PMID 33768639, 2021). "The promoter methylation levels of selected candidate genes (RASSF1A, DAPK1, SOX1, HOXA9, HIC1, SPARC, and SFRP1) were quantitatively evaluated by MethyLight in tumor DNA samples of patients with EOC." (PMID 34778370, 2021). "The role of SPARC in cancer is controversial as it has been shown to promote EMT and metastasis, but also to encompass tumor-suppressive functions in a context-dependent fashion." (PMID 34036938, 2021). "EMT is an important mechanism for the progression of CRC, and SPARC is an important EMT-related factor in CRC, which is involved in the interaction between tumor cells and stromal cells." (PMID 34349805, 2021). "The methylation level in the methylated EOC tumor samples ranged from 4 to 97% for HOXA9; 7–89% for HIC1; 4–97% for SOX1; 4–95% for DAPK1; 5–97% for SFRP1; 6–99% for SPARC and 4–98% for RASSF1A gene, respectively." (PMID 34778370, 2021). "In the tumor model, HSA–CDDP showed a similar tumor growth and survival rate to CDDP only in SPARC-expressing tumor models." (PMID 33114661, 2020). "Harnessing the strength of LCM, the enriched samples showed that both SPARC and COLIA1 are significantly enriched in both primary and metastatic tumours, highlighting that these markers are biological relevant in both settings." (PMID 31959771, 2020). "We observed a significant upregulation of SPARC in high grade HCC tissues, predicting unfavorable prognosis, and suggesting an important tumor-promoting effect of SPARC." (PMID 32670867, 2020). "Previous reports had demonstrated that SPARC and SPP1 were able to suppress the migration of DCs to lymph nodes, which would result in the accumulation of DCs at primary tumor site." (PMID 33240930, 2020). "HSA is a famous nanocarrier that can prolong the blood circulation time and enhance tumor accumulation by the EPR effect and SPARC-mediated active targeting." (PMID 33114661, 2020). "In turn, the ablation of SPARC in PMN-MDSCs reduces their suppressive activity and their capacity to sustain EMT and tumor growth." (PMID 32133298, 2020).
tumor (continued). "Collectively, the dual tumor-targeting feature of the Pt NPs, comprising both passive targeting via the EPR effect and active targeting via albumin/SPARC signaling, makes the Pt NP a promising candidate for NP-mediated drug delivery." (PMID 31992692, 2020). "Principal component analysis and random forest analysis were employed to further screen for six hub genes, including ISLR, COL1A2, CDH11, SPARC, COL3A1, and COL1A1, which exhibited a good ability to differentiate between tumor and normal samples." (PMID 32612640, 2020). "ECM components are produced by tumor cells and stromal cells and include collagen, FN1, proteoglycans, hyaluronic acid, and SPARC." (PMID 30736807, 2019). "Secreted protein acidic and rich in cysteine (SPARC) is a matricellular protein modulating cell-matrix interactions and was found up-regulated in tumor stroma." (PMID 31554208, 2019). "Our own recent tissue proteomics data offer to consolidate the contradiction, as we found increased abundance of SPARC protein in CRC as compared to normal tissue, but the protein was almost exclusively located in the tumor stroma." (PMID 31554208, 2019). "When an anti-human SPARC antibody was used, SPARC expression was low in U87MG-shSPARC tumor tissues." (PMID 31695779, 2019). "Genetic ablation of SPARC led to attenuated metastasis by decreased ECM deposition and impaired tumor cell-ECM interaction." (PMID 31300030, 2019). "Absence of SPARC expression within the tumors is a negative prognostic factor while high levels of SPARC protein expression, albeit rare, are associated with longer survival and could be protective against tumor aggressiveness." (PMID 30227835, 2018). "SPOCK1 is a glycoprotein, highly similar to SPARC, a well‐studied and characterized protein in the context of PDAC tumor growth." (PMID 28486750, 2017). "In contrast to the consistently observed low levels of SPARC found in the SPARC-transfected urosphere (TIC) cultures, the level of SPARC mRNA in the SPARC-transfected urosphere (TIC) generated tumor transplants was variable." (PMID 26783756, 2016). "The differential compartmentalization of SPARC may represent a state of aberrant homeostasis with increased inflammation that might be directly involved in urothelial cell transformation through the persistent release of inflammatory mediators and ROS, ancillary to tumor growth and metastasis." (PMID 27564266, 2016). "This is supported by the work of others which suggests a correlation of SPARC and TGFBI expression with tumor metastasis." (PMID 27622658, 2016). "Urospheres, potentially representing a population of tumor initiating cells (TIC), were isolated from the As+3-and Cd+2-transformed UROtsa cell lines stably transfected with SPARC." (PMID 26783756, 2016). "Three activated UPRs associated with immune activation were unique to CPA/6d-treated GL261(B6) tumors: EIF2AK2, IFNL1 and MAVS, while the two activated UPRs specific to GL261(scid) tumor responses, DMD and SPARC, have glial cell-related functions:." (PMID 27515027, 2016). "In fact, two recent studies suggested that SPARC modulates the expression of several ECM genes in a variety of cell types and are good candidates as conditioners of the tumor matrix proteins." (PMID 25786138, 2015). "Others argue that it’s involved in regulating other receptor protein expression-SPARC and MMP9 interact to regulate tumor metastasis.and controlling vascular formation." (PMID 26674531, 2015). "The in-vivo studies were particularly focused on the measurement of tumor burden, ascites fluid volume, number of ascites cells, VEGF and SPARC expression in tumor and VEGF concentration in plasma." (PMID 25890381, 2015). "For in vivo studies, we examined the tumor growth, ascites formation and the expression of VEGF and secreted protein acidic and rich in cysteine (SPARC) in tumor samples and only VEGF in plasma samples." (PMID 25890381, 2015).
tumor (continued). "Significant differences in GS were identified in relation to the expression profiles of ITGAV1, ITGA3, ITGA6, SPARC, MMP9, and MMP16, markers that were detected in the tumour samples examined." (PMID 26674523, 2015). "Moreover, it is hypothesized that the albumin-bound Nab-paclitaxel may selectively accumulate in the pancreatic stroma via its binding to secreted protein acidic and rich in cysteine (SPARC) matricellular glycoprotein which binds albumin and is overexpressed in tumor stroma." (PMID 24782785, 2014). "FN1 functionally connects a pair of coexpressed glycoproteins, FBLN1 and FSTL1, and SPARC is connected to IGFBP7, a tumor suppressor, which creates a functional link between a candidate tumor suppressor, PDGFRL, and a mesenchymal factor, FSTL1." (PMID 24944582, 2014). "The RAS pathway target genes LOXL2, SPARC and CTSB exert functions in the remodelling of the extracellular matrix, thereby favouring invasion and metastasis of tumour cells." (PMID 24875049, 2014). "Metastases generated from orthotopic pancreatic xenografts were also significantly reduced for SPARC-suppressed PDAC3 cells, as measured by luciferase imaging and normalized for primary tumor size." (PMID 25242334, 2014). "Based on the critical role of SPARC in tumor invasion and progression, we hypothesized that SPARC may also play a role in regulation of blastocyst implantation, especially in the process of trophoblast invasion which shares many similarities with invasion of tumor cells." (PMID 23935929, 2013). "Recently, more reports have shown that miR-29 family regulated tumorigenesis and tumor progression by targeting DNMT3A, DNMT3B, TIAM1, cyclin E, MMP2, ID1, SPARC and COL3A1." (PMID 23936390, 2013). "Previously identified alterations in the tumor microenvironment between SPARC+/+ and SPARC−/− mice were reassessed after losartan therapy." (PMID 22348081, 2012). "This suggests the possibility that, not only is SPARC capable of sensitising CRC cells to chemotherapy, but higher SPARC expression may be associated with other clinical features that the clinician thinks makes the tumour less aggressive and thus not require adjunctive therapy." (PMID 21818290, 2011). "Although further studies are required before these markers can be employed, the present results suggest that assessment of SPARC and FOXP3 expression in tumour tissue should improve the prognostic classification of stage II and III CRC." (PMID 21818290, 2011). "The SPARC and MMP-9 are known to interact to regulate many stages of tumour progression including ECM deposition, angiogenesis and metastasis." (PMID 20087345, 2010). "In the current study, from the expression pattern of SPARC and VEGF, we found that VEGF and SPARC were mainly expressed in tumor cells and MSC, respectively." (PMID 20565704, 2010). "Relative mRNA expression levels were significantly higher in tumor than in healthy samples for FN1, MMP1, PLAU and SPARC (Wilcoxon test for paired data, p ≤ 0.002)." (PMID 19835631, 2009). "In the tumor epithelium, there were only three genes (POSTN, periostin; SPARC, osteoconectin; SPARCL1, SPARC-like 1) that were significantly upregulated in IDC relative to DCIS." (PMID 19187537, 2009). "Key molecules investigated in ageing and in tumour biology include thrombospondin 1 (TSP1) and secreted protein acidic and rich in cystein (SPARC)." (PMID 18182993, 2008). "These genes are mainly characteristic of previously defined 'stromal' signature, but that are produced by both tumor and stromal cells including collagens, TIMP2, bFGF, vimentin and SPARC." (PMID 16042759, 2005). "SPARC is particularly overexpressed in the tumor microenvironment of TNBC, potentially facilitating the accumulation of albumin-bound therapeutics within both tumor cells and stromal components." (PMID 41489768, 2026).
tumor (continued). "SPARC can also induce EMT by upregulating the expression of EMT regulatory transcription factors SNAI1/2 and ZEB1 thereby inducing changes in cellular phenotype to promote tumour progression." (PMID 39865173, 2025). "Lastly, upregulation of SPARC inhibits TGF-β signaling, which also reduces tumor growth." (PMID 39796281, 2025). "In addition, PDFs secreted higher amounts of ITGB5 and SPARC, both of which are known to facilitate EMT and ECM remodeling, as well as Gal‐2, which contributes to tumor immunosuppression." (PMID 40411295, 2025). "The therapeutic potential of targeting MMP9, SPARC, and ITGA5 is heightened when considered in combination, as they are involved in different but complementary pathways of ECM remodelling, fibrosis, and tumor progression." (PMID 39865173, 2025). "In addition, shared hub genes across EAC and ESCC—such as COL1A1, SPARC, and MMP1—were enriched in ECM organization and cell adhesion processes, highlighting convergent tumor–stroma interactions." (PMID 40872572, 2025). "In addition, the on-chip expression profiling showed that the expression of the hepatic stellate cell-related genes FAP, SPARC, and TNC, especially FAP, was upregulated in tumor tissues compared to normal tissues." (PMID 38740736, 2024). "High SPARC expression in fibroblasts of OSCC may alter tumor microenvironment and thus affect tumor behavior." (PMID 38347494, 2024). "In their research, the lack of any chemical reactions preserved albumin bioactivities, and the albumin–pirarubicin complex showed greater tumor accumulation and tumor penetration through GP60- and SPARC-mediated biomimetic transport than pirarubicin and denatured albumin–pirarubicin." (PMID 38323081, 2024). "SPARC decreases type IV collagen levels and increases the expression of matrix metalloproteins (MMPs) that break down ECM components, thus modulating the tumor microenvironment and promoting tumor growth, invasion, metastasis, and angiogenesis." (PMID 37569556, 2023). "Furthermore, we analyzed publicly available single‐cell mRNA sequencing data and found that in TNBC, SPARC is expressed by different CAF subpopulations, including myofibroblasts and inflammatory fibroblasts that are involved in tumor‐related processes." (PMID 36346290, 2023). "Previous studies have suggested the possibility of an important pathway for albumin to pass through the BBB, as SPARC expression was maintained at a relatively low level in normal BBB capillaries, whereas it was upregulated by the tumor-derived secreted factor." (PMID 36945032, 2023). "RFS was not different in patients with SPARC‐positive (SPARC+) and SPARC‐negative (SPARC−) tumor cells." (PMID 36346290, 2023). "Positive fluorescence signals of ICG and SPARC protein were detected in U87MG tumor sections but not in U87MG-shSPARC tumor sections." (PMID 36614294, 2023). "Thus, HMF‐secreted SPARC inhibits adhesion and promotes motility, wound healing and invasion of MDA‐MB‐231 TNBC cells, highlighting its pro‐tumor role." (PMID 36346290, 2023). "Additionally, TIMP3, SPARC, IGFBP3, and IGFBP7 were highly expressed in the Mac_5 cluster, and these genes were involved in immunosuppression, tumor cell proliferation, and angiogenesis." (PMID 37533434, 2023). "Lastly, SPARC and more recently FTSJ1 gene product activities were proposed to be involved in both metastasis and tumour suppression." (PMID 36720500, 2023). "This suggests that once the complex is delivered to the TME by FcRn- or GP60-based shuttling of receptor-bound albumin across the tumor endothelium, the FHAB : HSA complex is retained in that space by binding to SPARC in a dynamic equilibrium with slow release." (PMID 38250068, 2023). "In parallel, the scRNA data from 15 PDAC tissues samples also showed higher infiltration of cells expressing SMC/fibroblast markers (PDPN, COL5A1, COL22A1, TIMP3, SPARC, WT1, GFPT2) in samples with higher proportions/fractions of MUC16-expressing tumor (epithelial) cells (n = 7)." (PMID 36816942, 2023).
tumor (continued). "Modulating SPARC, a collagen binding protein or Rab10, a regulator of basement membrane fibril formation (Isabella & Horne‐Badovinac, 2016) can ameliorate ECM accumulation in the fat body in tumour bearing animals, and in turn improve muscle integrity." (PMID 38014610, 2023). "In vitro evidence suggests that the matricellular protein SPARC has a tumor‐promoting role in triple‐negative breast cancer (TNBC)." (PMID 36346290, 2023). "We speculate that NCAPG might interact with LGALS1 to upregulate SPARC, leading to activate EMT signaling and augment tumor-derived vascular permeability." (PMID 35180865, 2022). "Our data suggested the two hub genes, SPARC and TPM1 may have key roles in the PDCA tumor microenvironment by regulating tumor-infiltrating immune cells." (PMID 35477379, 2022). "The non-cellular components of TME such as tenascin, periostin, SPARC, and collagen which overall contribute to the fitness of the tumor tissue, are mainly released by CAFs." (PMID 39086964, 2022). "Copper is also an essential cofactor of various metalloproteins known to be closely correlated with tumor growth and metastatic invasion (Mitogen-Activated Protein Kinase Kinase 1 (MAP2K1), lysyl oxidase (LOX) and lysyl oxidase-like, (LOXL), Secreted Protein Acidic and Cysteine Rich (SPARC)...)." (PMID 35456648, 2022). "MSCs could induce tumor matrix formation and EMT through the expression of SPARC in CRC, suggesting that SPARC in CRC cells may be used as a new target marker." (PMID 35281017, 2022). "Notably, tumor ECs were featured by upregulation of angiogenesis-related genes including collagens (e.g., COL4A1, COL4A2), PXDN, SPARC and HSPG2, as well as proliferation markers (e.g., MKI67, TOP2A)." (PMID 36138435, 2022). "Since SPARC overexpression enhances tumor-initiated permeability and vascular leakiness, which finally induces lung metastasis, and our study found that NCAPG knockdown could suppress SPARC expression." (PMID 35180865, 2022). "In both groups (Fra-2 cl 1 and cl 2), some interesting genes could be identified, e.g., in the Fra-2 cl 1 primary tumours LGALS1, ADRM1, and CTTN, which were upregulated and LUM (Lumican), MAN1A1, and SPARC, which were significantly downregulated." (PMID 34693476, 2022). "Various ECM components (hyaluronan, collagen, SPARC, α-SMA, tenascin C), that contribute to fibrosis, are overexpress in activated stromal cells (fibroblasts, myofibroblasts, stellate cells) and, in some cases, in tumor cells." (PMID 35447719, 2022). "Indeed, mouse tumors lacking SPARC show bigger tumors associated with abnormal vessels (less vessels but more permeable due to the decrease in BM and pericyte recovery around them), increased pro-tumor macrophage recruitment within primary tumor and enhanced metastasis." (PMID 34298680, 2021). "Serum albumin is stable, biocompatible, nontoxic, non-immunogenic, and can accumulate at tumor tissues or sites of inflammation attributing to the interaction of albumin with gp60 receptor and SPARC." (PMID 34869202, 2021). "In tissue samples, SPARC expression has been detected in stromal fibroblasts and MPM tumor cells." (PMID 33955203, 2021). "We observed a statistically significant correlation between tumor cell PDGFRB and stromal SPARC expression, whereas high stromal SPARC expression correlated inversely with the expression of mesothelial marker staining (combination of CK5, calretinin, and CK5/6)." (PMID 33955203, 2021). "After combining all three markers into one multivariable model, high tumor cell PDGFRB (HR = 1.01, 95% confidence interval [CI] = 1.00–1.03; p = 0.005) and high stromal SPARC (HR = 1.05, 95% CI = 1.00–1.11; p = 0.045) remained independently associated with survival." (PMID 33955203, 2021). "In tissues, the DNA methylation levels of the SPARC gene were significantly lower in paired non-neoplastic lungs (NLs) and normal lungs distant from tumor (NLDTs) than in NSCLCs (p = 0.002 and p = 0.0034 respectively)." (PMID 32580473, 2020).